COL6A1 (collagen type VI alpha 1 chain)
Diseases named in the same sentence as COL6A1 in open-access papers (continued):
Sharing a sentence is not in itself a finding about the gene and the disease.
tumor (73 papers, 2012 to 2025). "COL6 is primarily composed of three polypeptide chains (α1, α2, and α3), with the COL6A1 gene encoding the α1 chain that is often implicated in tumor growth and metastasis." (PMID 38887185, 2024). "Unique transcriptional profiles highlight a significant role for Col6a1+ CAFs in tumor-associated angiogenesis and reveal an increased metabolic and secretory phenotype for Col6a1− CAFs." (PMID 38203319, 2023). "Histological analysis of these tumours confirmed the high levels of collagen VI expression in abdominal cavity tumours from EV cells and the significant loss of Col6a1 staining in both KO lines." (PMID 36546396, 2022). "Up-regulation of COL6A1 in ccRCC was associated with poor prognosis of patients and promoted tumor growth in vivo." (PMID 35036081, 2022). "As COL6A1 was shown to associate with tumor progression and metastasis in several cancer types, we selected it for further analysis." (PMID 33391546, 2021). "Recent studies indicate that COL6A1 is differentially expressed in tumors and adjacent normal tissue, and is associated with tumor progression." (PMID 25895032, 2015). "In univariate Cox proportion hazard ratio analysis, age, T stage, positive lymph nodes, metastasis, tumor stage and high COL6A1 expression were significantly associated with poor prognosis in terms of OS of patients with ccRCC in the TCGA cohorts (P < 0.001)." (PMID 26317545, 2015). "Analysis of Col6a1+ CAF’s uniquely upregulated genes revealed significant enrichment in pathways related to blood vessel development, vascular endothelial proliferation, blood circulation, and hemostasis, indicating that Col6a1+ CAFs play a significant role in tumor-associated angiogenesis." (PMID 38203319, 2023). "Furthermore, COL6A1/2/3 expression levels revealed a clear correlation with immune subtypes, and COL6A1/2/3 were associated with tumor purity, that is, gene expression levels were generally higher in tumors with higher stromal scores and immune scores." (PMID 36167487, 2022). "The COL6A1 gene encodes the α1 chain and is usually involved in tumor metastasis." (PMID 26317545, 2015). "Thus, in VHL mutated patients, it can be speculated that COL6A1 upregulation indicates concurrence with inactivation of other tumor suppressors and may represent a signal of poor prognosis." (PMID 26317545, 2015). "P4HA1 regulates CD31 expression via COL6A1 during the transition of GBM stem‐like cells to tumor endothelial cells." (PMID 40226936, 2025). "COL5A2 and COL6A1 have been identified through pan-cancer analyses as significant factors in prognosis and tumor microenvironment modulation." (PMID 41139924, 2025). "COL6A1 is highly expressed in the malignant tumor cell subpopulation and has the potential to participate in extracellular matrix (ECM) and local lesion adhesion." (PMID 41176774, 2025). "The top 6 most abundant proteins encoded by COL6A1/2/3, COL1A1/2, and FBN1 detected in both NAT and tumor tissues and exhibited a similar trend in both composition and abundance." (PMID 40032993, 2025). "Amongst the differentially expressed EMT genes from that study, we find overlap with PTPRK-regulated genes including TGFB1, COL6A1, GPX3 and KLK10, as well as genes encoding LSR and PKP2, both of which are hyperphosphorylated in PTPRK KO tumours." (PMID 38904097, 2024). "In particular, CTHRC1+GREM1+ myCAF expressed high levels of collagens, including type-1 (COL1A1, COL1A6), type-3 (COL3A1), type-5 (COL5A2), and type-6 (COL6A1), which contribute to tumor cell migration and proliferation through collagen/integrin interactions." (PMID 39075108, 2024). "Taken together, these results implicate important roles of COL6A1 in GBM pathogenesis and its high expression associated with increased tumor malignancy and poor prognosis." (PMID 38887185, 2024). "Multi‐database single‐cell analysis heatmaps demonstrated upregulated expression of COL6A1 in GBM tumor cells." (PMID 38887185, 2024).
tumor (continued). "A recent study has demonstrated that collagen type VI alpha 1 (COL6A1) expression is significantly upregulated in OS tissues when compared to non-tumor tissues, especially in lung metastasis tissues." (PMID 36979391, 2023). "External cohort of 95 GBM patients by immunohistochemistry (IHC) assay demonstrated that ANXA1, COL6A1, and PDPN were significantly upregulated in tumor tissues of high‐risk GBM patients." (PMID 37434432, 2023). "For example, collagens, such as COL1A1, COL1A2, COL3A1, COL5A2, COL6A1, COL6A2, and COL6A3 are thought to mediate tumor progression and are associated with a poor prognosis in BCa." (PMID 37277784, 2023). "Increased levels of COL6A1 in tumor cells are packaged into exosomes and transported to activated CAFs, which, in turn, promote tumor invasion and metastasis by secreting TGF-β." (PMID 37197432, 2023). "In additions, clusters 4, 7 and 10 expressed a variety of collagen proteins including COL1A1, COL1A2, COL3A1, COL6A1 and COL6A3, which have been previously linked to abilities of proliferation, invasion, metastasis and drug resistance of tumor cells." (PMID 37644609, 2023). "Genetic depletion of collagen VI (Col6a1) reduced the rate of tumour initiation and growth, while overexpression of collagen I (Col1a1) in breast cancer models has been shown to enhance tumour formation and progression and increase the incidence of metastasis." (PMID 35760868, 2022). "Recent studies have shown that COL6A1 expression is significantly elevated in the tumor stem cells of GBM, is involved in interaction with the extracellular matrix, and is a key gene associated with anti-vascular endothelial growth factor therapy." (PMID 35855914, 2022). "RNA levels of COL6A1 were significantly increased in primary tumour samples versus levels in normal pancreas samples." (PMID 36546396, 2022). "Our results showed that the methylation levels of COL6A1/2/3 in tumor tissues were significantly lower than in normal tissues, as follows: COL6A1 in ESCA, BRCA, UCEC, and PRAD; COL6A2 in LIHC, HNSC, KIRP, and BLCA; COL6A3 in HNSC, BRCA, UCEC, COAD, and PRAD." (PMID 36167487, 2022). "What collagen VI staining remained in Col6a1 KO tumours appeared to colocalise with αSMA (ACTA2)-positive cells, which likely represent myofibroblast-like resident cells." (PMID 36546396, 2022). "All this evidence indicated that COL6A1 has a close relationship with tumor progression and was a novel biomarker of prognosis in different types of cancers, not a simple gene related to collagen anymore." (PMID 36357874, 2022). "Two KPC #127445 CRISPR lines with KO of Col6a1 (Col6a1.03 and Col6a1.04) were used alongside an EV control to generate abdominal cavity and diaphragm tumours." (PMID 36546396, 2022). "COL6A1, as a member of the collagen family, undertakes the main component of tumor ECMs, while P4HA1 can regulate the secretion of collagen, thus affecting the composition of ECM." (PMID 35494018, 2022). "The expression of COL6A1 was also increased in MRC5 cells following treatment with exosomes derived from COL6A1-expressing tumor cells (EXO/COL6A1)." (PMID 33391546, 2021). "We also performed immunochemistry (IHC) analysis and confirmed that COL6A1 levels were much lower in Six1−/− MCA205 tumor tissues than in WT tumor tissues." (PMID 34782761, 2021). "We also performed qRT-PCR and found that the COL6A1 mRNA expression levels were higher in the OS tissues (n = 22) than in non-tumor tissues (n = 7)." (PMID 33391546, 2021). "Other mutations within PyMT E2F1 KO tumors include COL5A2, with collagen V being a component of the interstitial matrix, COL6A1-3, with collagen VI being abundant in the tumor invasive front and several integrin and cadherin genes." (PMID 33947907, 2021). "COL6A1 is a member of the collagen family that is involved in numerous biological processes, including apoptosis, autophagy, stemness, differentiation, and tumor progression, including in RCC." (PMID 34359798, 2021).
tumor (continued). "An increased collagen deposition was shown to exert a fundamental role within the tumor microenvironment toward cancer growth and escape, and specifically COL6A1 was involved in both cell proliferation and metastasis of diverse malignancies as BC." (PMID 32143514, 2020). "In turn, for tumor stroma proteins, higher COL6A1 and MB expression was identified in the ITF according to the MS discovery analysis." (PMID 30185791, 2018). "The mean tumor volume of oe-COL6A1 group was larger than that of the oe-Mock group from Day 27 (P < 0.05)." (PMID 26317545, 2015). "The tumor volume of the COL6A1-transfected tumor was significantly larger than that of the Mock-transfected tumor on day 21 (33.38 vs. 89.05mm3, p < 0.05) and day 24 (42.02 vs.127.32mm3, p < 0.05)." (PMID 25895032, 2015). "The mean tumor weight of 7860-oe-Mock control group was less than that of the 7860-oe-COL6A1 group (0.41 g vs. 0.63 g, P = 0.06), although this difference was not statistically significant." (PMID 26317545, 2015). "We also investigated the effect of COL6A1 overexpression in a xenografted tumor model in nude mice in vivo." (PMID 26317545, 2015). "A recent study on the von Hippel-Lindau tumor suppressor (VHL, also known as E3 ubiquitin protein ligase) suggested that VHL inactivation decreases H3K4Me3 levels through JARID1C, which suppresses tumor growth as well as COL6A1 expression." (PMID 26317545, 2015). "Our IHC results showed that COL6A1 mainly existed in PCa tumor stroma, also known as reactive stroma." (PMID 25895032, 2015). "Three type VI COLs (encoded by COL6A1, COL6A2, and COL6A3) and two type I COLs (encoded by COL1A1 and COL1A2) constituted a significant proportion of the human colon ECM in NAT (55.6%) and tumor (31.8%) tissues." (PMID 40032993, 2025). "Analysis of tumor clones revealed SCC‐specific COL6A1+/ITGA5+ carcinoma cells which produce CXCL16." (PMID 40776410, 2025). "The strong fluorescence signal in the surrounding stroma may have masked or diluted the detection of COL6A1 specifically in tumor areas." (PMID 40776410, 2025). "Furthermore, we have also shown that COL6A1 is primarily expressed in tumor cells, with differential expression across tumor cell subtypes." (PMID 38887185, 2024). "Mutations in the FGFR3 gene are associated with low PD-L1 expression in BC, high expression of MAN1B1 is related to poor prognosis, high expression of COL6A1 in tumor cells promotes tumor growth and metastasis, and high expression of NXPH4 is associated with poor prognosis in BC." (PMID 39559360, 2024). "Based on these results, we verified if such COL6A1-orchestrated transcriptional signature could have a clinical impact in terms of tumor malignancy and patient survival." (PMID 37505240, 2023). "In particular, genes encoding collagen, including COL1A1, COL1A2, COL6A1, and COL6A3, are upregulated in tumor tissue and also highly expressed in late-stage cancer patients; they are predicted to interact with SDC1 and SDC4 in tumor cells to promote the pEMT phenotype of tumors." (PMID 38002057, 2023). "However, these genes had higher methylation levels in tumor tissues, including COL6A1 in KIRC, HNSC, THCA, KIRP, and COAD; COL6A2 in KIRC, LUSC, and BRCA; COL6A3 in LIHC and KIRC." (PMID 36167487, 2022). "Interestingly, both Col6a1 KO lines showed a trend for decreased tumour formation on the diaphragm and the peritoneum, which was significant for the Col6a1.04 line, despite no changes in mouse weight." (PMID 36546396, 2022). "In the present study, the correlation of COL6A1/2/3 with tumor stemness scores was explored." (PMID 36167487, 2022). "Although we cannot determine the origin of this surrounding collagen VI in Col6a1 KO tumours, the tumour-associated fibroblasts are the most likely source." (PMID 36546396, 2022). "All results suggest that exosomal COL6A1 in the extracellular environment may serve as a significant factor that promotes OS metastasis via tumor cell-fibroblast interactions." (PMID 33391546, 2021).
tumor (continued). "Expression of the COL6A1 protein in OS tissues (n = 181) was evaluated using immunohistochemistry, which revealed significantly higher expression in the OS tissues than in non-tumor tissues (n = 44)." (PMID 33391546, 2021). "In addition, we observed enhancement of not only CD8+ T cell infiltration but also DC infiltration and upregulation of CXCL9, CXCL10, GZMA, GZMB, and IFN-γ in Col6a1−/− tumor tissues compared with WT MCA205 tumor tissues." (PMID 34782761, 2021). "Furthermore, we found that COL6A1 enhanced anoikis resistance, which is a prerequisite for tumor metastasis." (PMID 33391546, 2021). "Substantial differences between tumor and neighboring healthy cortex were found in both interstitial matrix proteins, such as collagen 6 (COL6A1, COL6A2, COL6A3), and basement membrane components such as collagen 4 (COL4A1, COL4A2) and laminins (LAMA5, LAMA4, LAMB1, LAMB2, LAMC1)." (PMID 34884982, 2021). "Moreover, western blotting revealed significantly higher COL6A1 protein expression in the OS tissues than in case-matched non-tumor tissues (n = 41)." (PMID 33391546, 2021). "Among them, 13 proteins correlated with clinicopathological parameters and of these proteins, eight proteins were identified in neoplastic islands (ACTR2, CSTB, COL1A2, LTA4H, PGK1, NDRG1, S100A8, S100A9) and five proteins were identified in tumor stroma (COL6A1, FSCN1, ITGAV, MB, THBS2)." (PMID 30185791, 2018). "The majority of proteins (ACTR2, CSTB, LTA4H, PGK1, NDRG1, FSCN1, ITGAV, THBS2) significantly associated with clinical parameters showed lower expression in the ITF of the tumor stroma or neoplastic islands, with the exception of COL6A1, COL1A2, S100A8, S110A9, and MB." (PMID 30185791, 2018). "The increased availability of Mmp2 and Mmp12 as well as their substrates Col1a1, Col4a1, Col6a1 and LamC2 could indicate that the tumour cells generated foremost collagens, which can be cleaved by these Mmps." (PMID 30603057, 2018). "We demonstrated for the first time that COL6A1 could promote tumor proliferation in vitro and in vivo, suggesting its potential useful application to CRPC therapy." (PMID 25895032, 2015). "Moreover, the tumorigenesis study demonstrated that overexpression of COL6A1 promoted tumor growth in vivo." (PMID 26317545, 2015). "Our results showed that COL6A1 played an important role in tumor proliferation and might influence the transformation from ADPC to CRPC." (PMID 25895032, 2015). "COL6A1 overexpression promoted tumor growth in xenografted nude mice." (PMID 26317545, 2015). "Thus, we chose MRC5 cells (human embryonic lung fibroblasts) as a model to explore whether tumor cell derived COL6A1 could promote OS metastasis by activating CAF." (PMID 33391546, 2021). "Thus, based on our previous study, we speculated that COL6A1, as an extracellular protein, could have significant effects on the tumor-CAF interaction." (PMID 33391546, 2021). "We found that the EDEM3 expression in epithelial cells (marked by KRT18, EPCAM, KRT8) was significantly higher in tumour tissues with a large proportion of CAFs (marked by COL1A1, COL1A2, COL6A1, COL6A2) in the GSE188711 CRC dataset." (PMID 39754316, 2025). "Many signals favoring tumor cells were significantly activated in C2, such as integrin-related signals (COL9A3 − (ITGA2+ITGB1), JAM3 − (ITGAM+ITGB2), COL6A1 − (ITGA1+ITGB1)), immune suppression signals (CD99 − PILRA), etc.." (PMID 39391717, 2024). "Human collagen VI (COL6A1) is among the most predominant ECM proteins and is usually involved in tumor cell growth and related metastasis." (PMID 39559360, 2024). "As expected, we found that the value of 3 PDEARGs (ANXA1, COL6A1, and PDPN) and key DETF (WWTR1) were co‐expressed significantly higher in the tumor core than in the peripheral of GBM tissue, specifically in the neoplastic cells." (PMID 37434432, 2023). "Genes such as COL14A1, COL6A1, THBS2, COL4A2 and COL11A1 are involved in tumor migration and invasion." (PMID 37024829, 2023).
tumor (continued). "Col1a1, Col1a2, Col2a1, Col3a1, and Col5a2, which were commonly found in normal ECM of mouse, pig, and human breast tissues, were also identified in tumor ECM in addition to Col4a2, Col5a1, Col6a1, Col6a2, Col6a3, and Col7a1." (PMID 36547361, 2022). "The tumor suppressor miR-200 affects EMT and tumor cell metastasis by modulating the cell adhesion molecule E-cadherin and the ECM proteins COL6A1, LAMA5, LAMB2, LAMC2, and Fibronectin." (PMID 34769264, 2021). "A previous study indicated that COL6A1 promotes tumor metastasis partially via enhanced TGF-β signaling; we also observed that COL6A1 expression increased the expression of TGF-β based on the results from western blotting, qRT-PCR, and ELISA." (PMID 33391546, 2021). "As TGF-β signaling pathway plays an important role in EMT and tumor metastasis, we found that TGF-β increased the migration ability of OS cells in a dose-dependent manner and also profoundly induced COL6A1 mRNA and protein expression in OS cell lines." (PMID 33391546, 2021). "In particular, we found increased relative expression of MMP1, COL6A1, COL6A3, and TGFB1 in MCTS relative to tumor spheroids." (PMID 34035369, 2021). "Col6a1−/− mice on a background of MMTV-PyMT show decelerated hyperplasia and primary tumor formation." (PMID 32252260, 2020). "Staining for COL6A1, ITGAV, and MB proteins indicated a preferential localization in the tumor stroma, with staining also identified in neoplastic cells." (PMID 30185791, 2018). "In accordance with the results of our study, the restoration of COL6A1, which is expressed at low levels in the VHL−/− cell line 7860, promoted tumor growth." (PMID 26317545, 2015). "Although COL6A1 was not clearly detected in tumor regions by immunofluorescence, its expression was consistently enriched in Carcinoma 3 across scRNA‐seq and spatial transcriptomic data." (PMID 40776410, 2025). "In The Cancer Genome Atlas (TCGA) pancancer database, LUAD is one of multiple tumor types in which Col6a3 mRNA levels are higher in malignant than normal tissues, whereas Col6a1 and Col6a2 are not differentially expressed." (PMID 40166934, 2025). "This suggested that TEFT could promote tumor ECM remodeling, and COL6A1 might play a central role in mediating this effect." (PMID 38887185, 2024). "Together, these data indicated that COL6A1 was mainly expressed in GBM tumor cells, and TEFT might exert its antitumor effects by suppressing COL6A1 expression." (PMID 38887185, 2024). "Strikingly, examining the source of collagen gene expression (COL1A1, COL1A2, COL3A1, COL6A1, COL8A1, COL10A1) provided clarity that the majority of genes expressed in the tumor samples represent transcripts of the MSC-related component of the tissue microenvironment." (PMID 36940196, 2023). "Comparing metastatic tumours formed by PDAC cells with or without KO of Col6a1, it is clear that cancer cells are a significant source of collagen VI in this context." (PMID 36546396, 2022). "Since EMT-related clusters included both EMT-binding proteins (CAVIN1, COL6A1 and COL6A3) and EMT-driving partner proteins (CAVIN1 and COL6A1), a heterogeneous population of cells with EMT potential may reside within the tumor that drive metastasis." (PMID 36249004, 2022). "Additionally, four genes (i.e., COL6A1, SYDE1, ESCO2, and GIPC1) were differentially expressed between tumor and normal tissues." (PMID 34149809, 2021). "Moreover, previous reports indicated that MUC1, COPS6, HOTAIR, COL6A1 were served as biomarkers for PAAD and had tumor-suppressive or tumor-promoting ability." (PMID 34285140, 2021). "Cystatin-B (CSTB), leukotriene A-4 hydrolase (LTA4H), protein NDRG1 (NDRG1), and phosphoglycerate kinase 1 (PGK1) from the neoplastic island dataset and collagen alpha-1(VI) chain (COL6A1), integrin alpha-V (ITGAV) and myoglobin (MB) from the tumor stromal dataset were prioritized." (PMID 30185791, 2018).